TGM3 (transglutaminase 3)
Description:
Catalyzes the calcium-dependent formation of isopeptide cross-links between glutamine and lysine residues in various proteins, as well as the conjugation of polyamines to proteins. Involved in the formation of the cornified envelope (CE), a specialized component consisting of covalent cross-links of proteins beneath the plasma membrane of terminally differentiated keratinocytes. Catalyzes small proline-rich proteins (SPRR1 and SPRR2) and LOR cross-linking to form small interchain oligomers, which are further cross-linked by TGM1 onto the growing CE scaffold (By similarity). In hair follicles, involved in cross-linking structural proteins to hardening the inner root sheath.
Synonyms: TGE; UHS2
Tractability: Small molecule: a structure with a bound ligand is known; it has a high-quality binding pocket; it belongs to a druggable protein family. PROTAC: a small molecule that binds it is known.
Target class: Protein-glutamine glutamyl-transferase; Enzyme; Aminoacyltransferase
Gene: Protein-coding gene on chromosome 20 (2,296,001 to 2,341,079, forward strand). Ensembl gene ENSG00000125780.
Subcellular location: Cytoplasm
Gene Ontology:
Molecular function: calcium ion binding; catalytic activity; protein binding; protein-glutamine gamma-glutamyltransferase activity; structural molecule activity; acyltransferase activity
Biological process: keratinocyte differentiation; peptide cross-linking; hair follicle morphogenesis; protein modification process
Cellular component: cytoplasm; extracellular exosome; extrinsic component of cytoplasmic side of plasma membrane; protein-containing complex
Genetic constraint (gnomAD): Loss-of-function variants: 52 observed, 73.19 expected, observed/expected ratio (o/e) 0.71, 90% interval 0.57 to 0.89. The upper end of that interval is the gene's LOEUF score, 0.89, which puts it in group 3 of 6, group 1 being the genes least tolerant of losing a copy. Missense variants: 918 observed, 932.52 expected, observed/expected ratio (o/e) 0.98, 90% interval 0.93 to 1.04. Synonymous variants: 369 observed, 368.09 expected, observed/expected ratio (o/e) 1, 90% interval 0.92 to 1.09.
Homologues: Orthologues: chimpanzee TGM3 (98% identical), macaque TGM3 (93% identical), rabbit TGM3 (79% identical), dog TGM3 (78% identical), pig TGM3 (77% identical), guinea pig TGM3 (76% identical), mouse Tgm3 (76% identical), rat Tgm3 (76% identical), tropical clawed frog tgm3l.8 (45% identical), tropical clawed frog tgm3l.7 (42% identical), tropical clawed frog tgm6 (42% identical), tropical clawed frog tgm3l.2 (42% identical), and 2 more. Paralogues in human: TGM6 (51% identical), TGM5 (44% identical), TGM7 (40% identical), TGM2 (38% identical), TGM1 (34% identical), F13A1 (33% identical), TGM4 (32% identical), EPB42 (30% identical).
Diseases named in the same sentence as TGM3 in open-access papers:
TGM3 is named in the same sentence as 63 diseases in open-access papers, as found by Europe PMC text mining. Sharing a sentence is not in itself a finding about the gene and the disease. The quoted sentences say what the papers report.
dermatitis herpetiformis (10 papers, 2014 to 2025). "Dermatitis herpetiformis is a dermal manifestation of celiac disease and characterized by the presence of autoantibodies recognizing transglutaminase 3 (TG3)." (PMID 40064932, 2025). "Autoantibodies against the enzyme transglutaminase 3 (TG3) are characteristic to the gluten-sensitive skin disorder dermatitis herpetiformis (DH), which is an extraintestinal manifestation of celiac disease." (PMID 40064932, 2025). "This is analogous to transglutaminase 2 (tissue transglutaminase), the autoantigen in coeliac disease and transglutaminase 3 (epidermal transglutaminase), the autoantigen in dermatitis herpetiformis, the skin manifestation of gluten sensitivity." (PMID 38674899, 2024). "Dermatitis herpetiformis (DH) is an extraintestinal manifestation of gluten sensitivity, in which an autoimmune response is directed against transglutaminase 3 (TG3), an epidermal transglutaminase." (PMID 32967363, 2020). "Transglutaminase 6 (TG6), a member of the Transglutaminase family of protein-crosslinking enzymes and is closely linked to TG2 (the autoantigen in CD) and Transglutaminase 3 (TG3, the autoantigen in dermatitis herpetiformis)." (PMID 32244870, 2020). "In addition, TGM3 is the crucial autoantigen that recognizes T cells in dermatitis herpetiformis." (PMID 36685895, 2022). "Patients with dermatitis herpetiformis (DH) make auto‐antibodies to transglutaminase 2 (TG2) and transglutaminase 3 (TG3)." (PMID 37424036, 2023). "Transglutaminase 3 (TG3), the autoantigen of dermatitis herpetiformis (DH), is a calcium dependent enzyme that targets glutamine residues in polypeptides for either transamidation or deamidation modifications." (PMID 37798283, 2023).
celiac disease (7 papers, 2009 to 2025). An autoimmune genetic disorder with an unknown pattern of inheritance that primarily affects the digestive tract. "Investigations of these manifestations in celiac disease have identified a number of associated immune abnormalities, including B cell reactivity towards various autoantigens, such as transglutaminase 3, transglutaminase 6, synapsin I, gangliosides, and collagen." (PMID 30127251, 2018). "TGM3 (Transglutaminase 3) encodes protein involved in the later stages of cell envelope formation in the epidermis and hair follicle and has been associated with celiac disease and psoriasis." (PMID 22952805, 2012). "Immune reactivity to other autoantigens, including transglutaminase 3, actin, ganglioside, collagen, calreticulin and zonulin, among others, has also been reported in celiac disease." (PMID 19220902, 2009).
esophageal cancer (4 papers, 2007 to 2022). A primary or metastatic malignant neoplasm involving the esophagus. "Loss of TGM3 expression has been reported to have prognostic significance in oesophageal cancer." (PMID 24403052, 2014). "TGM-3 was down regulated in laryngeal carcinoma, esophageal carcinoma and OSCC." (PMID 29953521, 2018).
head and neck cancer (4 papers, 2013 to 2024). A primary or metastatic malignant neoplasm affecting the head and neck. "TGM3 was also associated with some forms of head and neck cancers, which would suggest a regulatory function in this anatomical region." (PMID 37268682, 2023). "Protein-glutamine gamma-glutamyltransferase E (TGM3) was proposed as a marker for some head and neck cancer types." (PMID 39201484, 2024). "In our previous study using oligonucleotide microarrays, we revealed that transglutaminase 3 (TGM3) was remarkably down-regulated in head and neck cancer (HNC)." (PMID 24289313, 2013). "TGM3 is involved in the transformation of the cell envelope in epidermis and hair follicles, but it is also a tumour suppressor and has been proposed as a progression marker for radio-chemotherapy of head and neck cancers." (PMID 33382739, 2020).
hepatocellular carcinoma (4 papers, 2020 to 2022). A malignant tumor that arises from hepatocytes. "TGM3 is either down- or upregulated in various cancers, including oral cancer, laryngeal cancer, esophageal cancer, colorectal cancer and hepatocellular cancer." (PMID 36685895, 2022). "TGM3 appeared to have prognostic significance in hepatocellular carcinoma (HCC)." (PMID 32872587, 2020).
laryngeal carcinoma (4 papers, 2013 to 2022). Carcinoma that arises from the laryngeal epithelium. "Studies have shown that loss of DNA heterozygous mutations and elevated CpG island methylation in the TGM3 promoter, which in turn silenced transcription and down-regulated TGM3 expression in laryngeal carcinomas." (PMID 36685895, 2022). "Several studies showed that the down-regulation of the TGM-3 gene is associated with a variety of human cancer types, including laryngeal carcinoma, esophageal and OSCC." (PMID 29953521, 2018).
uncombable hair syndrome (4 papers, 2017 to 2025). Uncombable hair syndrome (UHS), or pili trianguli et canaliculi, is a rare scalp hair shaft dysplasia. "The TGM3 gene product’s deficiency in humans has been linked to Uncombable Hair Syndrome, characterized by dry, frizzy, and wiry hair, while the Tgm3 knockout mice exhibit rough-looking, curly, or brittle hair." (PMID 29343290, 2018). "Interestingly, loss-of-function mutations in TGM3 are linked to uncombable hair syndrome, a condition characterized by unruly yet lustrous hair." (PMID 40699867, 2025).
atopic dermatitis (3 papers, 2020 to 2023). "Another study has revealed that TGM3 expression is higher in atopic dermatitis (AD) patients and is positively linked with disease severity, indicating that TGM3 is an autoallergen immune regulator that actively affected skin inflammation in AD." (PMID 36685895, 2022). "TGM3 was also revealed as an autoallergen in atopic dermatitis (AD) and was demonstrated to be actively involved in skin inflammation in this condition." (PMID 32872587, 2020).
esophageal squamous cell carcinoma (3 papers, 2007 to 2019). Esophageal squamous cell carcinoma (ESCC) is a type of esophageal carcinoma (EC) that can affect any part of the esophagus, but is usually located in the upper or middle third. "In esophageal squamous cell carcinoma, TGM3 could regulate cell proliferation, and the prognostic value of it was higher than those of the lymph node metastasis, intramural metastasis and vascular invasion status." (PMID 30884206, 2019). "Transglutaminase 3, which was underexpressed in the normal tissue of tumor patients in our study, was recently found to be downregulated in esophageal squamous cell carcinoma and head and neck squamous cell carcinoma by cDNA microarray studies comparing cancer and matching normal tissue." (PMID 18425214, 2007).
head and neck squamous cell carcinoma (3 papers, 2007 to 2020). A squamous cell carcinoma that arises from any of the following anatomic sites: lip and oral cavity, nasal cavity, paranasal sinuses, pharynx, larynx, and salivary glands. "The upregulation of TGM3 in HCC was demonstrated to make a similar contribution to the pathogenesis of HCC as was shown for its downregulation in head and neck squamous cell carcinoma, esophageal, and colorectal cancer." (PMID 32872587, 2020).
lymph node metastasis (3 papers, 2013 to 2022). "TGM3 expression is correlated with cellular dedifferentiation, cellular proliferation, increased invasiveness, lymph node metastasis and hematogenous recurrence, which results in high recurrence rate, rapid progression and unfavorable prognosis." (PMID 36685895, 2022).
melanoma (3 papers, 2020 to 2025). A malignant, usually aggressive tumor composed of atypical, neoplastic melanocytes. "The enrichment of these categories reflects the dysregulation of transcriptional programs typical of keratinocytes (e.g., SPRR1/2/3, KRT10/KRT16, LOR, IVL, EVPL, SCEL, TGM1/TGM3, CERS3, ACER1, DSP) and, above all, the epithelial crosstalk that influences melanoma biology." (PMID 41465101, 2025).
psoriasis (3 papers, 2012 to 2020). An autoimmune condition characterized by red, well-delineated plaques with silvery scales that are usually on the extensor surfaces and scalp. "We aimed to evaluate whether ablation of the TGM2 or TGM3 gene affected the severity of psoriasis markers in the context of imiquimod-treated TG3 and TG2 null mice." (PMID 32106600, 2020).
skin cancer (3 papers, 2018 to 2024). "Our results identify the complexity of known pleiotropic genes such as APOE, and suggest a new causal role for TGM3 in skin cancer." (PMID 38997278, 2024). "We also found a novel association for rs214830_G > C, a pQTL for TGM3 which was associated with skin cancer (ppHc = 0.75)." (PMID 38997278, 2024). "Furthermore, at the mRNA level, the expression pattern of TGM3 was crucially altered in BCC but not in other types of skin cancer." (PMID 32872587, 2020).
alopecia (2 papers, 2012 to 2025). Hair loss usually from the scalp. "More severe abnormalities in hair follicle morphogenesis were found in we/we wal/wal double mutants; thus, Tgm3 has a modifying effect on the wal gene, increasing alopecia in the double mutants." (PMID 40141208, 2025).
autism spectrum disorder (2 papers, 2013 to 2022). A spectrum of developmental disorders that includes autism, and Asperger syndrome. "Both SYNE1 and TGM3 have been highlighted in a study of de novo mutations in autism spectrum disorder." (PMID 36457050, 2022). "In this protein family, another member TGM2 is related with autism spectrum disorders, indicating that there is a possibility that TGM3 has underlying effect on mechanism of autism." (PMID 23369322, 2013).
breast carcinoma (2 papers, 2022). "Our data, suggest the implication of TGM3 deletion in early breast cancer onset." (PMID 36352274, 2022).
colitis (2 papers, 2022 to 2024). Inflammation of the colon. "Here, we report that natural isopeptide cross-linking by TGM3 is important for mucus homeostasis and protection of the colon from inflammation, reducing the risk of colitis." (PMID 35017479, 2022). "Taken together Tgm3−/− animals were significantly more susceptible towards the colitis-inducing effects of DSS as a faster disease onset was observed resulting in a decreased probability of survival." (PMID 35017479, 2022). "Finally, TGM3-deficient mice showed an early increased susceptibility to Dextran Sodium Sulfate-induced colitis." (PMID 35017479, 2022). "Higher DAI was maintained in the Tgm3−/− compared to WT animals until day 6, when the colitis also became established in the WT animals." (PMID 35017479, 2022). "Here the authors report that transglutaminase 3 activity contributes to homeostasis of the colonic mucus layer and the lack of this enzymatic activity leads to increased susceptibility against DSS-induced colitis in mice." (PMID 35017479, 2022). "The altered biochemical properties of mucus and its higher susceptibility to proteolytic degradation in the absence of TGM3 activity suggested that Tgm3−/− mice could be more susceptible to dextran sodium sulfate (DSS) induced colitis." (PMID 35017479, 2022). "In addition, Tgm3−/− mice are less protected against dextran sodium sulfate (DSS) induced colitis." (PMID 35017479, 2022). "Interestingly, two transcriptomic studies using either the 2,4,6-trinitrobenzene sulfonic acid or the adoptive T-cell transfer colitis model detected TGM3 downregulation after the establishment of the disease, thereby suggesting an impact of this enzyme for a healthy gut40,41." (PMID 35017479, 2022). "The late onset of moderate inflammation in the absence of Muc17 contrasted acute induction of severe colitis in C3GnT–/–, Vamp8–/–, and Tgm3–/– mice with defects in Muc2 glycosylation, secretion, and cross-linking." (PMID 39699961, 2024).
colorectal cancer (2 papers, 2021 to 2022). A primary or metastatic malignant neoplasm that affects the colon or rectum. "Another deleted gene, TGM3, is also know to play tumor suppressor roles in colorectal cancer by repressing EMT and PIK3/AKT signaling." (PMID 36352274, 2022). "In effect, TGM3 has been proposed to be a tumor suppressor by repressing EMT and PIK3/AKT pathway in colorectal cancer." (PMID 36352274, 2022).
COVID-19 (2 papers, 2022 to 2023). A disease caused by infection with severe acute respiratory syndrome coronavirus 2. "Further studies in a large population of patients with COVID-19 would be needed to elucidate if TGM3 could be related to the ability of SARS-CoV-2 to infect epithelial airway cells and act as a biomarker for pulmonary damage associated with COVID-19." (PMID 35760827, 2022). "Within the salivary proteins that were significantly increased in patients with COVID-19, five contributed most on the model: CAZA1, ACTN4, TGM3, CO4A, and ANXA4." (PMID 35760827, 2022).
skin inflammation (2 papers, 2020). "The mechanisms of skin inflammation in the case of DH and AD are most likely to be different as the authors showed that anti-TGM3 IgG but not IgA or IgM was increased in AD." (PMID 32872587, 2020).
bladder urothelial carcinoma (1 paper, 2022). "Regarding paired tumor lesions and normal tissues samples in the pan-cancer database, TGM3 was expressed at high levels in bladder urothelial carcinoma (BLCA), breast invasive carcinoma (BRCA), PRAD, KIRP, LIHC, KIRC and LUSC, but it was expressed at low levels in THCA and KICH." (PMID 36685895, 2022).
neck cancer (1 paper, 2021). "As a candidate cancer suppressor, low TGM3 expression is associated with a poor overall survival rate in patients with neck cancer." (PMID 33758613, 2021).
neuroblastoma (1 paper, 2022). Neuroblastoma (NB) is the most common solid, extracranial childhood tumor. "Furthermore, significant active coexpression of TGM3 with immune regulator genes was detected in PCPG, THCA, KIPAN, KICH, KIRC and neuroblastoma (NB)." (PMID 36685895, 2022).
nocardiosis (1 paper, 2022). Nocardiosis is a local (skin, lung, brain) or disseminated (whole body) acute, subacute, or chronic bacterial infection. "N. seriolae could significantly change the expression levels of mx, perforin, tgm3, il-1β and other genes in the kidney, liver, and spleen of diseased hybrid snakeheads, indicating that these genes have the potential to be developed as biomarkers for fish nocardiosis." (PMID 35154103, 2022).
oral lichen planus (1 paper, 2020). Oral lichen planus is a chronic inflammatory oral condition of unknown aetiology characterized by T-cell-mediated chronic immune response and abnormal epithelial keratinization cycle. "To finalize the list of disorders developing with TGM3 involvement, we have to mention the disease named oral lichen planus, which is the type of mucositis." (PMID 32872587, 2020).
pancreatic cancer (1 paper, 2022). "Further studies showed that high TGM3 expression had a certain risk impact on pan-cancer as high TGM3 expression levels were detrimental to the survival of several cancers, except for pancreatic cancer (PAAD)." (PMID 36685895, 2022).
Parkinson disease (1 paper, 2022). A progressive degenerative disorder of the central nervous system characterized by loss of dopamine producing neurons in the substantia nigra and the presence of Lewy bodies in the substantia nigra and locus coeruleus. "Furthermore, with the exception of TGM3, the absence of TG2 did not result in the increase in mRNA levels of other TG2 family members in a Parkinson’s disease model." (PMID 35159198, 2022).
type 2 diabetes (1 paper, 2017). "It is important to note that TGM2, TGM3, and TGM7 nsSNVs do not seem to be associated with any pathological phenotype except perhaps TGM2 heterozygous mutations associated with early-onset type 2 diabetes, an observation which has not been confirmed in animal experiments and large clinical cohorts." (PMID 28248968, 2017).
uterine carcinosarcoma (1 paper, 2022). A usually aggressive malignant neoplasm arising from the uterine corpus and less often the cervix. "The hazard ratios for TGM3 were significant for KIPAN, KIRC, LAML, SKCM, uterine carcinosarcoma (UCS), ALL and PAAD, among which TGM3 had the highest risk effect in UCS and was a protective factor in PAAD." (PMID 36685895, 2022).